MIR922 (microRNA 922)
Synonyms: hsa-mir-922; MIRN922
Gene: MicroRNA gene on chromosome 3 (197,674,496 to 197,674,576, reverse strand). Ensembl gene ENSG00000284146.
Gene Ontology:
Biological process: miRNA-mediated post-transcriptional gene silencing
Cellular component: RISC complex
Homologues: Orthologues: chimpanzee ptr-mir-922 (99% identical), macaque mml-mir-922 (91% identical).
Diseases named in the same sentence as MIR922 in open-access papers:
MIR922 is named in the same sentence as 2 diseases in open-access papers, as found by Europe PMC text mining. Sharing a sentence is not in itself a finding about the gene and the disease. The quoted sentences say what the papers report.
carcinoma (1 paper, 2025). A malignant tumor arising from epithelial cells. "Of those, eight (HOXA3, HOXA5, ATP10A, SOX2, MIR922, ADAMTSL1, KHDRBS2, and LITD1) were hypermethylated in at least one LS tumor group like here in FAP normal, whereas NEDD4L, and FOXP1 were hypermethylated in LS carcinomas and here in LS normal." (PMID 40753397, 2025).
MIR922 also shares sentences with these, for which no sentence is quoted: tumor (1 paper).